CX3CR1 (C-X3-C motif chemokine receptor 1)
Diseases named in the same sentence as CX3CR1 in open-access papers (continued):
Sharing a sentence is not in itself a finding about the gene and the disease.
amyloid (15 papers, 2013 to 2025). "In the APPPS1 and R1.40 mouse models of amyloidosis, Cx3cr1 deficiency results in a gene-dose dependent reduction in fibrillar Aβ (fAβ) burdens in early disease, suggesting that a loss of CX3CR1 is beneficial in Aβ pathogenesis." (PMID 35764973, 2022). "Our previous studies using murine models of AD deficient in Cx3cr1 have provided insights into the divergent role of fractalkine signaling in amyloidosis and tauopathy." (PMID 35764973, 2022). "Other studies using CX3CR1-deficient mice showed exacerbated levels of phospho-Tau and elevated Tau pathology in Tau transgenic mice, while CX3CR1 deficiency reduced amyloid load in AD mouse models with numerous Aβ deposits." (PMID 25056803, 2014). "In amyloid mouse models, knockdown of CX3CR1 has beneficial effects on amyloid deposition, likely as a result of increased microglial phagocytosis of Aβ." (PMID 39219300, 2025). "Because in vivo imaging necessitated the use of animals haploinsufficient for CX3CR1, we first verified that microglia in this model showed the same downregulation of homeostatic markers and β2AR with age and amyloid pathology." (PMID 38464247, 2024). "The role of the fractalkine/CX3CR1 axis in AD is still under debate since cx3cr1 knockout (cx3cr1−/−) has shown opposite effects in amyloidosis and tau pathology models." (PMID 39272998, 2024). "In this report, we investigate how microglial responses to Aβ shaped by CX3CR1 drive long term neurotoxicity in the 5xFAD model of amyloid disease." (PMID 35764973, 2022). "AD-induced amyloidosis causes release of fractalkine (CX3CL1) from neurons, which by stimulating its receptor CX3CR1 that is present on microglia and several leukocyte types, promotes neural and vascular inflammation and reduced eNOS and nitric oxide (NO)." (PMID 30519973, 2019). "Ablation of CX3CR1 in APP-transgenic mice led to reduced amyloid plaque burden most likely due to an increased phagocytic activity of CX3CR1-negative microglia in these mice." (PMID 29371603, 2018). "Future studies to specifically deplete peripheral CX3CR1+ myeloid cells using bone marrow transplantation are needed to determine the potential contribution of peripheral CX3CR1+ cell population in amyloid plaque formation." (PMID 28606182, 2017). "In addition to aging, we also observed a specific upregulation of CD22 in Aβ-containing microglia in the amyloid mouse model PS2APP CX3CR1-GFP." (PMID 34140954, 2021). "Crossing the CX3CR1−/− mice to CRND8 transgenic mice that harbor a gene encoding a mutant human amyloid precursor protein also resulted in reduced Aβ deposits, with the CX3CR1-deficient microglia phagocytosing amyloid plaques and displaying higher proliferation rates in the plaque regions." (PMID 23507975, 2013). "For example, it has been reported that, similar to CX3CR1 deficiency, amyloid precursor protein/presenilin-1 (APP/PS1) mice lacking CX3CL1 showed reduced amyloid pathology, and expression of obligate sFKN in this context did not improve or exacerbate this effect." (PMID 32410624, 2020).
colorectal cancer (15 papers, 2013 to 2026). A primary or metastatic malignant neoplasm that affects the colon or rectum. "Another study showed that the co-expression of FKN and CX3CR1 in colorectal cancer cells (FKN-CX3CR1 axis-positive tumors) was associated with a significantly longer period of disease-free and disease-specific survival." (PMID 38731899, 2024). "CX3CR1 may act as a prognostic biomarker in colorectal cancer because its expression is associated with immune marker expression, immune cell infiltration levels, and macrophage polarization." (PMID 38731899, 2024). "In a report using mesenchymal stem cells (MSCs) for the treatment of colorectal cancer, MSCs induced CX3CR1-high expressing macrophages and promoted M1 polarization, which inhibited tumor growth by promoting CX3CL1 secretion." (PMID 40508161, 2025). "This study aimed to investigate the expression levels of CX3CR1 in Ly108-CD62L-CD8+ Tex cells in the CT26 colorectal cancer model." (PMID 40236705, 2025). "The results showed that both DAC and 5-FU significantly promoted the expansion of CD62L+CD8+ Tpex cells and enhanced the expansion and effector function of CX3CR1+ Texint cells in the colorectal cancer tumor model." (PMID 40236705, 2025). "CX3CR1 was expressed in a histological grade- and stage-dependent manner in histopathological samples obtained from patients with colorectal cancer." (PMID 38731899, 2024). "CX3CR1 expression determines the recruitment and regulation of immune-infiltrating cells and macrophage polarization in colorectal cancer." (PMID 38731899, 2024). "Studies report that CX3CR1 is also involved in regulating the tumor inflammatory microenvironment and serves as a protective biomarker in colorectal cancer." (PMID 37994325, 2023). "CX3CR1 was selected as a hub gene, and the expression was confirmed in colorectal cancer (CRC) patients and cell lines." (PMID 35140706, 2021). "For example, the CX3CR1 gene has been identified as a hub gene in colorectal cancer, i.e., a gene that interacts with many other genes in the gene network and commonly plays a critical role in biological processes and gene regulation in the course of the disease." (PMID 38731899, 2024). "Therefore, the combination of MSCs and anti-PD-1 antibody may be a therapeutic approach for colorectal cancer via the CX3CR1/CX3CL1 axis." (PMID 40508161, 2025). "Therefore, the silencing of CX3CR1 may promote the proliferation and migration of colorectal cancer cells." (PMID 38731899, 2024). "Relevant studies have shown that CX3CR1 is crucial for the recruitment of infiltrating immune cells and is significantly related to clinical stage, histological type, histological grading and distant metastasis, of some tumors (e.g., colorectal cancer, pancreatic cancer)." (PMID 38532933, 2024). "CX3CR1 is known to promote migration of CX3CR1+ tumor cells and our anti-CX3CR1 antibody reduces the migration of CX3CR1+ CT26 colorectal carcinoma." (PMID 37771579, 2023). "Interestingly, however, while CX3CR1 expression in cancer is generally associated with invasiveness and metastasis, the coexpression of CX3CR1 and CX3CL1 by the same cell type, as occurs in human colorectal cancer cells, acts as a retention factor, limiting tumor spreading to metastatic sites." (PMID 28791023, 2017). "This subpopulation was significantly different from the transition-state CD8+ Texint cells, characterized by high Cx3cr1 expression, and terminally exhausted CD8+ Texterm cells, which highly expressed Entpd1 and Havcr2 in colorectal cancer; it was in line with the results of related studies." (PMID 40236705, 2025). "Their absolute numbers were markedly elevated, with the number of CX3CR1+ Texint cells exhibiting an approximately 7.0-fold increase in the 5-FU group compared with a 1.5-fold increase in the DAC group, which was consistent with the progression of growth in all groups of colorectal cancers." (PMID 40236705, 2025).
colorectal cancer (continued). "Differential gene profiling analysis of tumor vs. non-tumor samples from surgical colorectal cancer patients showed that CX3CL1 and CX3CR1 were significantly upregulated in tumors." (PMID 40508161, 2025).
coronary artery disease (15 papers, 2010 to 2025). "The CX3CR1 T280M variant is associated with a lower risk for coronary disease, while the V249I variant presents the opposite effect on the prevalence of coronary disease." (PMID 39125578, 2024). "Nonetheless, there are two single nucleotide polymorphisms of the CX3CR1 molecule that have been identified and that contribute towards the risk of developing coronary artery disease, namely CX3CR1-V249I and CX3CR1-T280M." (PMID 37510939, 2023). "CX3CL1 receptor (CX3CR1) up-regulation is known to be associated with coronary artery disease and with the development of CVD." (PMID 31109070, 2019). "The chemokine receptors CCR2 and CX3CR1 are important in the development of coronary artery disease." (PMID 20836883, 2010). "This allows for the risk stratification methods using CX3CR1 gene coding to quantify the risk of coronary artery disease independent of other factors." (PMID 37510939, 2023). "Similarly, in a previous study fractalkine and its receptor (CX3CR1) were increased in circulation as well as in atherosclerotic plaque in coronary artery disease, providing a potential link between uremic toxicity and accelerated atherogenesis." (PMID 30249039, 2018). "Recent data demonstrated the enhanced expression of CXCL1 and its receptor (CX3CR1) in coronary artery disease that could be downmodulated by statin therapy." (PMID 24307998, 2013). "Accordingly, CX3CR1 expression on CD8 T cells, endothelial production of CX3CL1, and T cell CX3CL1-mediated adhesion and chemotaxis are all increased in people with coronary artery disease, and attenuated following six months of statin therapy, which decreases risk of CVD events." (PMID 32976527, 2020). "CX3CR1 and CX3CL1 contribute to CVD morbidity in persons without HIV infection: polymorphisms in CX3CR1 are associated with coronary artery disease; numbers of CX3CR1-expressing cells and plasma CX3CL1 levels predict plaque rupture in unstable angina." (PMID 32976527, 2020). "Both CX3CR1 and CCR2 are important in the development of coronary artery disease." (PMID 20836883, 2010). "Therefore, our results further imply that CCR2 and CX3CR1 have independent, non-redundant roles in vascular inflammation and the later stages of coronary artery disease." (PMID 20836883, 2010).
Insulin resistance (15 papers, 2014 to 2025). Increased resistance towards insulin, that is, diminished effectiveness of insulin in reducing blood glucose levels. "In GDM, higher levels of CX3CL1/CX3CR1 in the placenta are linked to increased insulin resistance (IR) and an inflammatory response." (PMID 37928902, 2023). "In conclusion, we demonstrate a moderate and reproducible protective effect of Cx3cr1 deficiency on glucose intolerance and insulin resistance." (PMID 26393344, 2015). "Moreover, deficient fractalkine-CX3CR1 signalling exacerbates diet-induced insulin resistance, hepatic steatosis, and adipose tissue inflammation." (PMID 35871167, 2022). "Moreover, loss of CX3CR1 in DIO mice exacerbated insulin resistance, inflammation, and steatohepatitis by inducing a shift to M1 macrophages in adipose tissue." (PMID 34360773, 2021). "CX3CR1 deletion also promoted proinflammatory macrophage accumulation in adipose tissue and liver as well as insulin resistance." (PMID 34948325, 2021). "There is a possibility that differences in blood glucose levels seen in CX3CR1−/− and IL-1a/b KO mice compared to WT following insulin administration are rather due to insulin resistance than impaired counterregulatory responses." (PMID 30996341, 2019). "Studying multiple cohorts of mice at different time points, we detected consistent modest protective effects of Cx3cr1-/- on diet induced insulin resistance mediated partly through preservation of hepatic insulin sensitivity and signaling." (PMID 26393344, 2015). "On the other hand, another study using a different strain of Cx3cr1 deficient mice found no changes in obesity-induced inflammation, insulin resistance, and adipose macrophage accumulation, as compared with control mice." (PMID 34360773, 2021). "Furthermore, since CX3CL1 levels in the blood are linked to indicators of insulin resistance in people with GDM, researchers investigated whether resveratrol therapy might reduce CX3CL1/CX3CR1 production." (PMID 37928902, 2023). "Since FCH is associated with a high risk of cardiovascular disease, the objective of the present study was to assess the presence of alterations in the CX3CL1/CX3CR1 axis in patients with FCH and to evaluate the influence of insulin resistance (IR) and sex." (PMID 41153665, 2025). "Insulin resistance–metabolic syndrome patients have been reported to benefit from strategies concerning stimulation of VSMC survival and reduction in FKN/CX3CR1 signaling to promote plaque stability through an IRS2-dependent signaling." (PMID 32532282, 2020). "CX3CR1 and CCR2 may independently regulate monocyte phenotype and macrophage polarization, and contribute to adipose tissue inflammation and insulin resistance, and the progression of NAFLD." (PMID 34360773, 2021). "High-fat diet failed to trigger obesity in Cx3cr1−/− mice and the CX3CL1-CX3CR1 axis did not seem to promote inflammatory macrophage accumulation in adipose tissue or liver, thereby preventing inflammation-induced insulin resistance." (PMID 24741577, 2014).
tauopathy (15 papers, 2014 to 2026). Neurodegenerative disorders involving deposition of abnormal tau protein isoforms (tau proteins) in neurons and glial cells in the brain. "In particular, deletion of Cx3cr1 promotes hallmark neuropathological features of tauopathy including tau hyperphosphorylation and aggregation." (PMID 37464408, 2023). "By contrast, in the hTau model of tauopathy, loss of Cx3cr1 enhances microglial activation, increases accumulation of Gallays+ neuronal NFTs and exacerbates cognitive dysfunction." (PMID 35764973, 2022). "Emerging evidence found that TIA1 reduction increased microglial phagocytosis in advanced tauopathy 57, while a recent study reported that CX3CR1 driven knockout of TIA1 in microglia greatly reduced microglial inflammation 58, aligning with our findings." (PMID 41424856, 2026). "P301S microglia also displayed downregulation of Cx3cr1, indicating consistent CX3CR1 dysregulation between mouse microglia and human peripheral immune cells in the context of tauopathy." (PMID 37464408, 2023). "Altered CX3CL1/CX3CR1 signaling has been demonstrated to regulate the pathological changes in both animal models of tauopathies and AD patients." (PMID 33672982, 2021). "Another major study of tauopathies focuses on the fact that microglial receptor CX3CR1 plays a key role in the internalization of tau, a progress that also been indicated to been crucial in the synucleinopathy pathogenesis." (PMID 30787269, 2019). "It should be noted that microglial CX3CR1 signaling has been shown to affect tau phosphorylation in models of tauopathy." (PMID 26634348, 2015). "This suggests CX3CR1 may have potential utility as a peripheral biomarker of tauopathy and warrants further study in larger cohorts." (PMID 37464408, 2023). "Moreover, we identified CX3CR1 as a potentially novel peripheral marker of tauopathy, suggesting parallel changes in CX3CR1 in microglia and peripheral leukocytes in the course of tau-mediated neurodegeneration." (PMID 37464408, 2023). "Moreover, the DAMs showed a reduced expression of various homeostasis genes, such as- P2Y12 and CX3CR1 in AD and Tauopathy mice models." (PMID 37221563, 2023). "Given that microglial homeostasis is dysregulated in tauopathy, our novel findings—coupled with the well-defined relationship between CX3CR1 and tauopathy—provide a promising foundation for further investigation of this gene as a peripheral biomarker of tauopathy." (PMID 37464408, 2023). "The protective role of Cx3cl1/Cx3cr1 is also seen in models of AD (APPPS1 and R1.40), ALS (TgSOD1G93A), tauopathy and PD." (PMID 24655482, 2014). "Interestingly, deficiency of the microglial housekeeping gene, Cx3cr1, impairs the Nrf2 response in a model of tauopathy and microgliosis is not rescued by sulforaphane indicating the critical role of Cx3cr1 in inflammatory homeostasis." (PMID 32823544, 2020). "In addition, adoptive transfer of microglia lacking CX3CR1 induces tauopathy in wild type mice." (PMID 31572168, 2019). "In addition, in a model of tauopathy, a humanised MAPT transgenic mouse also lacking Cx3cr1 showed altered microglial activation, enhanced tau phosphorylation and aggregation as well as poorer spatial working memory." (PMID 24655482, 2014).
asthma (14 papers, 2009 to 2025). "It has been demonstrated that transfer of CD4+ T cells from wild type mice into CX3CR1 deficient mice restores the clinical features of asthma, highlighting the therapeutic potential of the CX3CL1/CX3CR1 axis." (PMID 24799766, 2014). "The CX3CR1-activated pathway included Asthma, Nicotine Addiction, Olfactory transduction, Phototransduction, and Viral protein interaction with cytokine and cytokine receptor." (PMID 38147020, 2023). "In the non-classical CD14+CD16++ subset, the percentage of cells expressing CX3CR1 was significantly decreased in patients with mild (67 ± 4; p < 0.0001, moderate (74 ± 3.5; p = 0.003) or severe (74 ± 3.6; p = 0.003) asthma compared to healthy controls (85%)." (PMID 31700522, 2019). "Our objective was to determine whether CD14, CD16, CCR2 and CX3CR1 on monocyte subsets are potential indicators of asthma severity." (PMID 31700522, 2019). "CX3CR1 expression in lung epithelial cells may also have implications for other respiratory diseases such as asthma." (PMID 26107373, 2015). "In contrast, CX3CR1 inhibition decreased cell counts in the BAL and chemokines levels in a model of asthma; however, the study was focused on eosinophilia and T cells and therefore is not comparable with the presented results." (PMID 33791319, 2021). "The differential expression of CD16, CX3CR1 and CCR2 on monocyte subsets in peripheral blood indicates modulation of the inflammatory response and suggests a role for monocytes in asthma pathogenesis." (PMID 31700522, 2019). "A significant decrease was observed in the percentage of cells expressing CX3CR1 in the intermediate CD14++CD16+ subset in patients with mild (75 ± 4; p = 0.002) and moderate (78 ± 3; p = 0.004) asthma compared to healthy (88%) controls." (PMID 31700522, 2019). "We here report high-level production in E.coli of 4 human GPCRs, namely chemokine receptors (hCRs) CCR5, CCR3, CXCR4 and CX3CR1 that are directly involved in HIV-1 infection, asthma and cancer metastasis." (PMID 19223978, 2009). "This differential expression of CD16, CX3CR1 and CCR2 on the monocyte subsets in peripheral blood indicates that monocytes may modulate the inflammatory response in asthma." (PMID 31700522, 2019). "CX3CR1 expression was also lower, with a lower percentage of cells expressing CX3CR1 in the non-classical CD14+CD16++ subset in all patients with asthma and this was inversely related to the percentage of cells expressing CCR2." (PMID 31700522, 2019). "CX3CR1 MFI was also significantly decreased (p = 0.0146) on the non-classical CD14+CD16++ subset in patients with severe asthma compared to healthy control subjects." (PMID 31700522, 2019). "The increase in CCR2 expression and decrease in CX3CR1 on CD16+ monocytes has not, to our knowledge, been described before in asthma and this association suggests a role for monocytes in asthma pathogenesis." (PMID 31700522, 2019). "This is consistent with our finding that monocyte subsets have decreased CD16+ associated with increased asthma severity and the suggestion that monocytes newly released from the bone marrow have not fully reduced CCR2 and acquired CX3CR1 in addition to CD16." (PMID 31700522, 2019). "It was reported that this intermediate CD14+CD16+ subset (same subset is also referred to as CD14++CD16+ or CD14highCD16+) was expanded in patients with allergies and asthma and expressed a number of M2 surface markers such as CD163, CX3CR1, IL-4R, TGF-β1 and IL-10." (PMID 24358127, 2013). "Thus these changes in CCR2 and CX3CR1 expression in intermediate and non-classical monocyte subsets indicate a more phagocytic phenotype and increased likelihood of endothelial damage adversely affecting asthma progression." (PMID 31700522, 2019). "The percentage of monocytes expressing CX3CR1 in the classical CD14++CD16− subset was not changed when patients with mild, moderate or severe asthma were compared with healthy controls." (PMID 31700522, 2019).